RN7SL826P (RNA, 7SL, cytoplasmic 826, pseudogene)
Gene: Miscellaneous RNA gene on chromosome 8 (117,163,968 to 117,164,255, forward strand). Ensembl gene ENSG00000240151.
Homologues: Orthologues: chimpanzee Metazoa_SRP (97% identical), macaque Metazoa_SRP (80% identical). Paralogues in human: RN7SL126P (77% identical), RN7SL3 (77% identical), RN7SL1 (76% identical), RN7SL220P (76% identical), RN7SL45P (76% identical), RN7SL2 (76% identical), RN7SL664P (76% identical), RN7SL828P (76% identical), RN7SL448P (75% identical), RN7SL679P (74% identical), RN7SL186P (74% identical), RN7SL296P (74% identical), and 704 more.